APOE (apolipoprotein E)
Diseases named in the same sentence as APOE in open-access papers (continued):
Sharing a sentence is not in itself a finding about the gene and the disease.
disc degeneration (2 papers, 2017 to 2019). "These altered concentration levels of the major matrix proteins in NP and AF tissues of APOE-knockout rabbits exhibit the characteristic features of structural and functional deterioration of IVDs, which underline the fundamental problem of disc degeneration." (PMID 29099857, 2017). "Alike human NP cells of different disc degeneration grades, NP cells of APOE-knockout and wild-type rabbits showed significantly different in vivo cell population densities (p<0.0001) and similar in vitro proliferation rates." (PMID 31751427, 2019). "The T2-weighted MRI signal characteristics of the lumbar IVDs revealed accelerated disc degeneration in APOE-knockout rabbits as compared to that in the wild-type rabbits." (PMID 29099857, 2017). "T2-weighted MRI analysis of the lumbar spines in APOE-knockout rabbits exhibited more advanced disc degeneration grade (DDG IV) as compared with the disc degeneration grade (DDG II) of the wild-type rabbits." (PMID 29099857, 2017). "Since the impact of APOE-knockout on rabbits IVD degeneration has not yet been investigated, we determined to examine and compare disc degeneration in APOE-knockout and wild-type rabbits of matching age." (PMID 29099857, 2017).
dissection (2 papers, 2012 to 2014). The separation and isolation of tissues for surgical purposes, or for the analysis or study of their structures. "In this model (Ang II/ApoE−/−), an AAA was defined as a ≥50% increase in aortic diameter or the onset of dissection." (PMID 23226500, 2012).
dysautonomia (2 papers, 2022 to 2024). An acute or chronic disorder, affecting the sympathetic or parasympathetic nervous system. "Some mechanisms already described in the literature may explain the process of dysautonomia observed in ApoE-KO animals." (PMID 38570516, 2024).
edema (2 papers, 2016 to 2021). An abnormal accumulation of fluid beneath the skin, or in one or more cavities of the body. "For example, apoE polymorphism appears to play a significant role in determining outcomes following ICH, as the apoE4 isoform is associated with increased cerebral edema and neurologic morbidity." (PMID 27713572, 2016). "Therefore, the cause of death of the PD-fed hApoE2 rats might be the formation of vascular fat embolism, while severe pulmonary edema could be the cause of the sudden death of the ApoE KO-PD rats." (PMID 34361033, 2021).
erectile dysfunction (2 papers, 2013 to 2024). Persistent or recurrent inability to achieve or to maintain an erection during sexual activity. "Recently our laboratory showed that sildenafil, a phosphodiesterase 5 (PDE5) inhibitor which has been widely used for erectile dysfunction and pulmonary hypertension treatment, restores endothelial function in apoE-/- mice." (PMID 23981672, 2013).
Erythema (2 papers, 2017 to 2021). Redness of the skin, caused by hyperemia of the capillaries in the lower layers of the skin. "The erythema, scales, infiltration, and total score of IMQ-induced ApoE−/− mice continued to increase with the number of days." (PMID 33762935, 2021). "Dose- and APOE ε4 genotype-dependent ARIA were observed, as was injection site erythema." (PMID 29221491, 2017).
fracture (2 papers, 2022 to 2025). "Falls are a major determinant of hip fractures, and the allele of the APOE signal associated with increased hip fracture risk was also associated with increased risk of falls, suggesting that this signal has an effect on hip fracture risk via risk of falls and not via bone strength." (PMID 36260985, 2022).
Gaucher disease (2 papers, 2022). Gaucher disease (GD) is a lysosomal storage disorder encompassing three main forms (types 1, 2 and 3), a fetal form and a variant with cardiac involvement (Gaucher disease - ophthalmoplegia - cardiovascular calcification or Gaucher-like disease). "Clinical evaluation of ApoE and neurofilament light chain (Nf-L) as biomarkers of Gaucher disease (GD)-associated neurodegeneration." (PMID 35972072, 2022). "Still, a number of risk factors for LBD are linked to other neurodegenerative diseases: BIN1 (also AD), TMEM175 (Transmembrane protein 175; also PD), SNCA (also PD), APOE (also AD), and GBA (glucocerebrosidase; also PD, Gaucher’s disease)." (PMID 36421678, 2022).
glucose metabolism disorders (2 papers, 2023 to 2025). "Additionally, polygenic HTG, rare lipid-related variants beyond APOE, and glucose metabolism disorders were significantly linked with TG levels, explaining 30% of TG variance in a cross-validated model." (PMID 40806502, 2025). "Additionally, there was a notable improvement in HFD-induced glucose metabolism disorders and IR in ApoE-/- mice." (PMID 38062308, 2023).
gram-negative bacterial infections (2 papers, 2022 to 2025). Infections caused by bacteria that show up as pink (negative) when treated by the gram-staining method. "While our comprehension of the precise role of lipid-poor or free APOE remains incomplete, there is a hypothesis suggesting that APOE may exert a neutralizing effect on Gram-negative bacterial infections." (PMID 39880097, 2025). "Although the role of lipid-poor/free APOE in the skin is not fully known, we hypothesized that the APOE may have a neutralizing effect on Gram-negative bacterial infection." (PMID 35740451, 2022). "Together, our data suggest that APOE may have an important role in controlling inflammation during Gram-negative bacterial infection." (PMID 35740451, 2022).
hip fracture (2 papers, 2022 to 2024). Traumatic or pathological injury to the hip in which the continuity of either the femoral head, femoral neck, intertrochanteric or subtrochanteric regions is broken. "The association between APOE ɛ4 and fall-, any fracture-, and hip fracture-related hospitalizations, obtained over 14.5 years from linked health records, was examined using multivariable-adjusted Cox-proportional hazard models." (PMID 38766839, 2024).
Hunter syndrome (2 papers, 2023 to 2025). "In contrast, SWAP variants with either an ApoE or RAP12x2 inserts outperformed untagged IDS in correcting or preventing most peripheral and CNS manifestations in a murine Hunter syndrome model." (PMID 41023195, 2025).
hypopituitarism (2 papers, 2022 to 2023). A condition of diminution or cessation of secretion of one or more hormones from the anterior pituitary gland. "Polymorphism of the ApoE gene also affects development of hypopituitarism." (PMID 36788181, 2023). "Recently, we showed that certain polymorphisms of apolipoprotein-E (APO-E) synthesized after TBI in the central nervous system, including the hypothalamus–pituitary region, reduce the risk of pituitary insufficiency, and for this, one must take into account individual differences in treatment." (PMID 36555341, 2022).
Infertility (2 papers, 2021). "The follicular microenvironment in patients with EMT is closely related to infertility; thus, ApoE expression was detected in the FF of patients with EMT." (PMID 34867826, 2021).
intrahepatic cholangiocarcinoma (2 papers, 2023 to 2024). A carcinoma that arises from the intrahepatic bile duct epithelium in any site of the intrahepatic biliary tree. "CIQB might affect prognosis by regulating the TME because a study found that intrahepatic cholangiocarcinoma (ICC) with APOE+C1QB+ subtype of macrophage infiltration was associated with the chronic inflammation subtype of ICC and poor prognosis." (PMID 38022584, 2023). "Additionally, an APOE+/C1QB+ macrophage was identified in intrahepatic cholangiocarcinoma, which could reshape the chronic inflammation and predict a poor prognosis." (PMID 38346944, 2024).
ischemic cardiomyopathy (2 papers, 2021 to 2022). Ischemic cardiomyopathy is a cardiomyopathy in which a weakness in the muscle of the heart due to inadequate oxygen delivery to the myocardium with coronary artery disease being the most common cause. "Our study aims to analyze the involvement of apoE in non-ischemic cardiomyopathy.METHODS AND RESULTS: Serial echo-cardiographic measurements were performed in old wildtype and apoE deficient (apoE-/-) mice." (PMID 34816004, 2021).
leprosy (2 papers, 2022 to 2024). Leprosy is a chronic infectious disease affecting primarily the skin and peripheral nervous system. "In leprosy, the expression levels of APOE and CYP27A1 were positively correlated with the levels of 18 immune cell types." (PMID 38273053, 2024). "In the E-MTAB-10318 dataset, APOE, CYP27A1, FADS1, and SOAT1 showed higher expression levels in leprosy compared to the control group." (PMID 38273053, 2024).
limb ischemia (2 papers, 2023). A ischemia that involves the limb. "Finally, we tested if ABCB5+ MSCs restore ER Ca2+ using the Sarco-/endoplasmic reticulum ATPase 2a (SERCA2a)- Phospholamban (PLN) axis in both in-vitro cell models as well as in-vivo hind limb ischemia model in Apolipoprotein E knock-out (ApoE−/−) mice, which model chronic on acute hypoxia." (PMID 36759868, 2023).
Listeria infection (2 papers, 2021). "With respect to other APPs, it is worth mentioning the impaired innate response to Listeria infection in ApoE-deficient mice, as another example of how a decrease in APP expression could impact the host response to this pathogen." (PMID 34858876, 2021).
membranous nephropathy (2 papers, 2018 to 2020). "On the other hand, LPG is a heterogenous disease in pathology, especially the recently discovered mutation APOE‐Toyonaka with membranous nephropathy‐like kidney pathology, suggesting that genetic factor is significant in LPG." (PMID 32441489, 2020).
metabolism (2 papers, 2017 to 2023). "Several ApoE polymorphisms have been linked to impaired glucose metabolism and a high risk of T2DM (Higuchi, Izquierdo & Haeusler, 2018)." (PMID 37123009, 2023).
metachromatic leukodystrophy (2 papers, 2019 to 2020). A rare lysosomal storage disorder characterized by intralysosomal accumulation of sulfatides in various tissues, leading to progressive deterioration of motor and neurocognitive function. "In our data, in addition to APOE, we found that the lipoprotein receptor LSR and the lysosomal enzyme ARSA—a gene in which homozygous mutations cause metachromatic leukodystrophy —were elevated in HAM." (PMID 32610143, 2020).
metastatic melanoma (2 papers, 2020). A melanoma that has spread from its primary site to another anatomic site. "These evidences sustain the activation of LXR receptor in the regulation of APOE expression in metastatic melanoma, similarly to what reported in astrocytes by Abildayeva and coworkers, thus enhancing the maturation of PMEL into amyloid fibrils." (PMID 32749065, 2020).
Moyamoya disease (2 papers, 2021 to 2023). Moyamoya disease (MMD) is a rare intracranial arteriopathy involving progressive stenosis of the cerebral vasculature located at the base of the brain causing transient ischemic attacks or strokes. "We collected 33 patients with MMD and 28 patients without MMD to investigate the potential of APOE as a biomarker for moyamoya disease." (PMID 37228412, 2023).
myocarditis (2 papers, 2024). Myocarditis is a condition that is characterized by inflammation of the heart muscle (myocardium). "It has also been shown that APOE signaling is associated with myocarditis pathology and that inhibition of APOE signaling reduces the pathological progression of myocarditis." (PMID 39571156, 2024).
nasopharyngeal carcinoma (2 papers, 2022 to 2025). A carcinoma arising from the nasopharyngeal epithelium. "Nevertheless, studies on the relationship between ApoE and the prognosis of nasopharyngeal carcinoma remain unreported." (PMID 40495209, 2025). "In conclusion, it is believed that this study is the first retrospective undertaking to investigate the relationship between baseline ApoE and nasopharyngeal carcinoma." (PMID 40495209, 2025). "This study represents the first large-scale cohort exploration of the relationship between ApoE within blood lipids and the prognosis of nasopharyngeal carcinoma." (PMID 40495209, 2025). "The 352 patients were divided into two groups according to the pretreatment ApoE level of nasopharyngeal carcinoma patients to analyze their various survival prognoses." (PMID 40495209, 2025). "According to that study, patients with nasopharyngeal carcinoma had a statistically significant increase in serum ApoE levels along with statistically significantly (p < 0.05) more common metastases to the lymph nodes and invasion of surrounding tissues." (PMID 35892323, 2022). "The specific mechanism by which ApoE affects the prognosis of nasopharyngeal carcinoma remains unclear and further exploration is required in future studies." (PMID 40495209, 2025). "An elevated pretreatment serum ApoE level is indicative of a poorer prognosis for nasopharyngeal carcinoma patients and is independent of other known prognostic factors." (PMID 40495209, 2025). "This preliminary study explores the prognostic value of pretreatment peripheral serum apolipoprotein E (ApoE) in patients with non-metastatic nasopharyngeal carcinoma (NPC)." (PMID 40495209, 2025).
oral squamous cell carcinoma (2 papers, 2020). "Similarly, Jayakar indicated that knockdown of APOE expression can reduce the level of MMPs by regulating the AP-1 signaling pathway and thus reduce the invasion and metastasis of oral squamous cell carcinoma." (PMID 32766727, 2020). "In addition, the cellular uptake of gold nanorods (AuNRs) in Cal 27 oral squamous-cell carcinoma has been enhanced by an apolipoprotein E (ApoE) corona." (PMID 32664362, 2020).
peritoneal effusion (2 papers, 2020 to 2023). "Expression of apoE is significantly associated with a better 5-year survival outcome in patients who presented with peritoneal effusions at the time of diagnosis, inferring a protective role of apoE in the survival of EOC." (PMID 32462055, 2020).
peritonitis (2 papers, 2013 to 2015). Inflammation of the peritoneum (tissue that lines the abdominal wall and covers most of the organs in the abdomen). "The expression of ApoE mRNA was also significantly higher in Cx3cr1GFP/GFP peritoneal Mφs (prepared from thioglycollate-elicited peritonitis) when compared to WT-Mφs cultured for 24 h in the presence of CX3CL1 (Fig3F)." (PMID 25604058, 2015). "iNOS production was significantly decreased in the peritonitis model in ApoE−/− mice when compared to WT mice." (PMID 23977160, 2013).
phenylketonuria (2 papers, 2025 to 2026). Phenylketonuria (PKU) is the most common inborn error of amino acid metabolism and is characterized by mild to severe mental disability in untreated patients. "As is known from phenylketonuria, genetic variation is not destiny; therefore, research that explores the pathways through which APOE variation works could provide useful information toward alleviating some of the health inequalities in cognitive ageing." (PMID 40386430, 2025).
Postural instability (2 papers, 2022 to 2023). A tendency to fall or the inability to keep oneself from falling; imbalance. "GBA and APOE ε4 status did not predict progression to postural instability." (PMID 35577512, 2022).
primary progressive aphasia (2 papers, 2024 to 2025). Primary progressive aphasia (PPA) is a neurodegenerative disorder, characterized by a primary dissolution of language, with relative sparing of other mental faculties for at least the first 2 years of illness. "Along these studies is a preliminary study on patients with primary progressive aphasia, which reported the APOE ε2/ε4 genotype as a possible risk factor for the condition." (PMID 40018689, 2025).
renovascular hypertension (2 papers, 2015 to 2023). High blood pressure secondary to renal artery stenosis. "RORα agonist prevented vulnerable plaque rupture and suppressed intraplaque hemorrhage in renovascular hypertension combined with low shear stress of hypercholesterolemic ApoE−/− mice." (PMID 36834872, 2023).
sarcoidosis (2 papers, 2022 to 2025). Sarcoidosis is a multisystemic disorder of unknown cause characterized by the formation of immune granulomas in involved organs. "However, upregulation of SPP1 was more modest, and unlike NL and NXG macrophages, sarcoidosis lesional macrophages strongly overexpressed APOE, VAT1, TLR8, and ALDH1A1 among other genes." (PMID 39989459, 2025).
Schnyder corneal dystrophy (2 papers, 2013 to 2024). Schnyder corneal dystrophy (SCD) is a rare form of stromal corneal dystrophy characterized by corneal clouding or crystals within the corneal stroma, and a progressive decrease in visual acuity. "Remarkably, germline mutations in TERE1 cause a rare disease of elevated corneal cholesterol and lipid deposition called Schnyder's Corneal Dystrophy, SCD, and these mutations alter binding to APOE, HMGR, and TBL2." (PMID 23919967, 2013).
severe combined immunodeficiency (2 papers, 2022 to 2024). Severe combined immunodeficiency (SCID) comprises a group of rare monogenic primary immunodeficiency disorders characterized by a lack of functional peripheral T lymphocytes resulting in early-onset severe respiratory infections and failure to thrive. "CD4+ T cells from ApoE-/- mice were transferred to ApoE-/- mice crossed with severe combined immunodeficiency (SCID) strains of mice, leading to greatly increased fatty streak lesions compared to immunocompetent ApoE-/- mice." (PMID 39399488, 2024). "Furthermore, mice with SCID (severe combined immunodeficiency) and apolipoprotein E (ApoE) knockout mice, showed a reduction in aortic lipid striae in 73% of cases, compared to mice with a normal immune system." (PMID 35634284, 2022).
sinus (2 papers, 2012 to 2023). "ApoE−/− mice treated with ARE had significantly smaller aortic sinus lesions, lower numbers of macrophages in the aortic wall, and decreased expression levels of adhesion molecules (VCAM-1 and ICAM-1) in the vessel wall compared with control mice." (PMID 22536886, 2012). "To accessed the reason why vismodegib could reduce aortic sinus lesions and vulnerability in vivo, we measured the composition of plaque in different groups of apoE−/− mice." (PMID 37963874, 2023).
Skeletal myopathy (2 papers, 2017 to 2021). "Particular emphasis is given on i) the abundant evidence from the ApoE deficient mouse model and the role of western-type of diet and ii) on skeletal myopathy and oxidative stress-induced myofibre damage from human studies." (PMID 28688452, 2017). "Statin administration reduced the exercise capacity in ApoE-/- mice infected with lentivirus vector, but not in ApoE-/- mice infected lentivirus expressing miR-1a inhibitor, further supporting that statin induces skeletal myopathy through induction of miR-1a in mice." (PMID 33864447, 2021).
skin aging (2 papers, 2022 to 2025). The gradual irreversible changes in structure of skin that occur as a result of the passage of time.. "While we identified a key regulatory role and potential mechanism for p16 in regulating HFD-induced skin inflammaging, we used ApoE KO mice to construct a HFD-induced skin aging model and simulate pathological processes; however, this is a study weakness." (PMID 36457728, 2022).
skin inflammation (2 papers, 2018 to 2021). "A recent study showed that ApoE−/− mice resulted in skin inflammation and hair discoloration/loss, indicating a possible functional role of APOE in hair follicle formation." (PMID 33410284, 2021).
sporadic CJD (2 papers, 2011 to 2021). "There is a study to suggest that APOE ε4 carriers have nearly twofold increased risk of sporadic CJD." (PMID 34565486, 2021). "In this work, we investigated for the first time, APOE and PRNP genotypes simultaneously in 474 AD and 175 sporadic CJD (sCJD) patients compared to a common control population of 335 subjects." (PMID 21799773, 2011).